IDH1 (isocitrate dehydrogenase (NADP(+)) 1)
Diseases named in the same sentence as IDH1 in open-access papers (continued):
Sharing a sentence is not in itself a finding about the gene and the disease.
cancer (continued). "Whether there are also three-dimensional chromatin interactions that are common across all IDH1/2 mutant cancers remains to be explored." (PMID 31727977, 2019). "Additional studies indicate that IDH1/2 inhibition could increase the efficacy of conventional cancer therapies." (PMID 31010244, 2019). "Multiple clinical trials are underway using this inhibitor in IDH1 mutant cancers." (PMID 31288436, 2019). "Among all the observed variants in the 585 cancer genes annotated in OncoKB16, a repository of curated cancer genes, IDH1 R132H and BRAF V600E are the two most tissue-specific variants with NMIs of 0.18 and 0.13, respectively, followed by GTF21 L424H with an NMI of 0.08." (PMID 31796730, 2019). "A pan-IDH1/2 inhibitor is suggested to be a second-generation drug in IDH-mut cancers." (PMID 30857299, 2019). "IDH1 and/or IDH2 mutations occur in glioma, and rarely in other cancers." (PMID 31881713, 2019). "It has been observed that IDH1 inhibition sensitizes defined types of cancers to chemotherapy." (PMID 31010244, 2019). "The expression level of IDH1-R132H, which is the most common mutation type, correlates with poor outcomes in several cancers, such as gastrointestinal cancer and nonenhancing diffuse glioma." (PMID 30153799, 2018). "Although IDH1 have consistently been reported take part in the genesis of many cancers, the correlation between IDH1 expression and ccRCC outcomes remains unclear." (PMID 30153799, 2018). "(b) Schematic putative signaling pathway illustrating IDH1-modulated cancer cell invasion." (PMID 29661250, 2018). "Patients with IDH1-mutant cancers might be candidates for treatment with IDH1-specific therapies that are currently under development." (PMID 29581876, 2018). "The metabolic activity of IDH1/2 has been tied to cancer epigenetic mechanisms." (PMID 30024920, 2018). "Of these primary cancers, 75% were classified into seven subtypes, defined by either specific gene fusions of ETS transcription family members (ERG, ETV1, ETV4, and FLI1) or mutations (SPOP, FOXA1, and IDH1)." (PMID 29581876, 2018). "Pathway enrichment analysis revealed that IDH1 knockdown significantly altered cancer-related pathways such as the mitogen-activated protein kinase (MAPK), peroxisome proliferator-activated receptor signaling pathways, regulation of cell adhesion, and cell migration." (PMID 29661250, 2018). "However, our study revealed that low expression of IDH1 was associated with adverse ccRCC patients’ prognosis, which was inconsistent with that in NSCL cancer." (PMID 30153799, 2018). "Almost all reported cases of these mutations have been heterozygous, and inactivating alterations such as frameshifts, deletions, and nonsense mutations have not been observed in IDH1 or 2 in cancer." (PMID 28785398, 2017). "This metabolic vulnerability has been exploited as therapeutic modality where depletion of NAD+ using small molecule inhibitors targeting the salvage NAD+ synthesis enzyme nicotinamide phosphoribosyl transferase resulted in strikingly selective cytotoxicity in IDH1 mutant cancer cells." (PMID 28785398, 2017). "IDH1-mutant SHH MBs were determined to be CIMP+, confirming that these mutations lead to epigenetic consequences reminiscent of those reported in other IDH1/2-mutant cancers." (PMID 28726821, 2017). "Based on that, the combined treatment of these cancer cells with olaparib, an inhibitor of PARP-mediated single strand DNA repair, and the DNA-damaging agent temozolomide has been proposed as a promising treatment modality for IDH1 mutated tumors." (PMID 28785398, 2017). "It has been reported that IDH1 and IDH2 neomorphic mutations are prevalent in various cancers." (PMID 28827794, 2017). "H3/IDH1 wildtype pHGGs have previously been shown to be a diverse group of tumors with mutations in many cancer pathways, but have not been directly linked to any particular epigenetic driver as is the case with H3 and IDH1 mutant tumors." (PMID 29084603, 2017).
cancer (continued). "The status of mutant IDH1 in cancers has been revealed in recent years." (PMID 27863386, 2016). "Third, the degradative pathway and efficiency of IDH1 may be transformed in cancer cells at odds with normal cells." (PMID 27863386, 2016). "First, cancer cells upregulate cellular IDH1 in response to rapid proliferation and increased ROS." (PMID 27863386, 2016). "Recent research implies that reduction of the NADPH production capacity in IDH1 mutant cells may be a contributing factor in cancer formation." (PMID 26008980, 2015). "The cancer-associated mutant IDH1 or IDH2 exclusively produces D-2-HG, but not L-2-HG, both of which are byproducts of normal mitochondrial metabolism." (PMID 25825982, 2015). "An unexpected result of the cancer hotspot panel sequencing approach was the identification of mutations in genes usually associated with non-epithelial malignancies, such as IDH1 R132H/R132C, JAK3 V722I, and FLT3 A680V." (PMID 25656989, 2015). "This could be a consequence of genetic alterations in enzymes regulating epigenetic patterns, such as gene mutations found in human myeloid malignancies, including DNMT3a, TET2, IDH1, IDH2, EZH2, or ASXL1." (PMID 24944583, 2014). "However, both studies utilized cancer cell lines with wild type IDH1 into which the mutant IDH1 was introduced." (PMID 22885298, 2012). "Heterozygous point mutations in IDH1 and IDH2 occur in a significant portion of human cancers." (PMID 21326614, 2011). "Mutant IDH1 expression can up-regulate hypoxia inducible factor 1α (HIF-1α), a transcription factor that has been implicated in promoting angiogenesis and malignant behavior of cancer cells." (PMID 21326614, 2011). "We also include a state-of-the-art literature review about IDH1 and IDH2 molecular biology, biochemical properties, and the role of their mutations in cancer development and progression, along with insights into regional variations in cancer biology and treatment response." (PMID 40182999, 2025). "Notably, mutation of the NRAS gene, which is linked to cell division in cancer, was found to be the variable most correlated with CPP uptake, followed closely by mutation of IDH1, which is associated with the expression of isocitrate dehydrogenase 1, a key player in the Krebs Cycle." (PMID 38365724, 2024). "This possibility is supported by the finding that D-2HG (produced by mutated IDH1-2) competitively inhibits SDH, resulting in the accumulation of succinyl-CoA and hyper-succinylation of mitochondrial proteins, ultimately leading to apoptosis resistance, a hallmark of cancer." (PMID 39438765, 2024). "Notably, recent findings show that IDH1-mutant cancer cell–derived oncometabolite 2-hydroxyglutarate (2HG) could directly affect CD8+ T cell biology in the TME." (PMID 39133578, 2024). "IDH1/2 are frequently mutated in cancers, but not in HCC, and the gain-of-function IDH1/2-mutantenzymes lead to the accumulation of the oncometabolite D-2-hydroxyglutarate, resulting in aberrant DNA and histone methylation by competitively inhibiting enzymes such as TET and JMJD." (PMID 38699532, 2024). "In addition, vorinostat causes increased DNA double-strand breaks and functional homology-directed repair deficiency by down-regulating the expression of the DNA repair factors breast cancer 1 (BRCA1) and Rad51, resulting in increased cell death in IDH1 mutant cancer cells." (PMID 38988323, 2024). "The PI3K/AKT/mTORC1‐HIF1α axis additionally promotes glucose metabolic reprogramming, leading to the overexpression of GLUT1, thereby suggesting that both GLUT1 and mutant IDH1 could serve as potential targets for various cancers, including colorectal cancer and glioblastoma." (PMID 39584783, 2024).
cancer (continued). "Inhibition of the production of D2HG production by IDH1 mutation inhibitor ivosidenib or catabolism of D2HG by overexpression of D2HGDH may reverse D2HG induced muscle proteolysis and slow the progression of cancer cechexia." (PMID 37741882, 2023). "Interestingly, computational analysis of the TCGA pan-cancer data characterized both gene expression and DNA methylation as the most effective predictors of the somatic mutation state, as previously demonstrated with the oncogenic mutations of the IDH1 and IDH2 genes in cancer." (PMID 38067407, 2023). "Fumarate and succinate antagonize the roles of α-KG In addition to IDH1 and IDH2, germinal and somatic mutations of fumarate hydratase (FH) and succinate dehydrogenases (SDHA, SDHB, SDHC, SDHD, and SDHAF2), encoding FH and SDH enzymes, are common in a number of human cancers." (PMID 34050894, 2022). "Ivosidenib efficiently killed IDH1R132 mutant cancer cell lines at low nanomolar IC50 in vitro, drastically and rapidly reduced 2-HG levels in a mouse xenograft model derived from HT-1080 fibrosarcoma cell line and led to the differentiation of IDH1-mutated AML cells from patients ex vivo." (PMID 35740380, 2022). "Studying the IDH1 structure (PDB ID 5YFN), we find that G97 is also involved in a direct interaction with isocitrate, and therefore will also likely damage enzymatic activity; additionally, G97 has been previously implicated in human cancers and is known to accumulate 2‐hydroxyglutarate." (PMID 36321551, 2022). "Mechanisms causing CIMP are heterogeneous, including mutations in IDH1/2 and SETD2 that were previously reported in specific cancer types, as well as reported for the first time here in new cancer types; the novel overexpression of BORIS/CTCFL spanned several cancer types." (PMID 35134107, 2022). "Recent cancer genome sequencing studies revealed mutations in many epigenetic modifiers that are associated with various cancers, such as DNMT3A in acute myeloid leukemia, IDH1/2 in glioblastoma, CREBBP/EP300 in small-cell lung cancer and ARID1A in gastric cancer." (PMID 35973998, 2022). "Therefore, T001-0657 is a powerful inhibitor that could be used to further investigate the biological role of IDH1-R132C and has the potential to provide therapeutic strategies for a wide range of cancer indications." (PMID 36160383, 2022). "IDH1 or 2 deletion would be expected to be associated with loss of IDH function causing perturbed metabolism, due to a reduction in cellular 2OG and/or NADPH, with a possible decrease in the efficiency of DNA damage repair and consequently increased risk of cancer." (PMID 34854890, 2021). "Oxidative stress has been recognized as a hallmark of cancers, which promotes tumor growth and malignant progression, especially for cancers with intrinsic altered metabolic signatures, such as SDHB-mutated PCPGs and isocitrate dehydrogenase 1 (IDH1)-mutated malignancies." (PMID 31979226, 2020). "Other GLS inhibitors were also tested after manipulation of IDH1 R132H, Compound 2 or CB-839 inhibits proliferation preferentially in IDH mutated cells, but it has a poor BBB penetration, and compound 968 was able to sensitize cancer cells to mTOR-targeted therapies in mouse xenograft models." (PMID 32993063, 2020). "Importantly, D-2HG accumulation and NAPRT hypermethylation that occurs in mutant IDH1/2 cancers could be potential candidates for NAMPT inhibitor trials as they lack NA pathway." (PMID 32111066, 2020).
cancer (continued). "Second, the survival of patients with BRAFAMP and IDH1/2MT was comparable to that of patients with BRAF mutations and greater than that of patients with BRAFAMP and IDH1/2WT, probably because the IDH1/2 mutation and 2-HG can induce oxidative stress, autophagy, and apoptosis in cancer cells." (PMID 33489866, 2020). "In addition, IDH1/2 targeted therapy has variable responses among IDH mutant cancer types." (PMID 31727977, 2019). "This suggests that some areas of the chromosomes may not be the target of DNA methylation changes induced by IDH1/2 mutation in cancers and may be regulated by other epigenetic mechanisms." (PMID 31727977, 2019). "Finally IDH1 is an example of a gene with more specific effects in certain types of cancer." (PMID 31530827, 2019). "Furthermore, all IDH1 mutant cancers were found to have a more closely related methylation profile compared to other cancers which may reflect a similar mechanism of epigenetic instability." (PMID 30598662, 2018). "In addition, isocitrate dehydrogenases 1 and 2 (IDH1 and IDH2) are frequently mutated in cancer." (PMID 29434587, 2018). "Among all tested cancer genes, whether deleted, amplified or mutated, IDH1 was the only one with negative log2 odds ratio, i.e. it was mutually exclusive of FHIT deletion, meaning that cancers with significantly mutated IDH1 genes do not show FHIT allele loss." (PMID 29254236, 2017). "Thus it appears that major cancer networks can be strongly influenced by IDH1/2 gene status." (PMID 27624942, 2016). "In addition to the downregulated expression of TET genes, it was reported that decreased 5-hmC expression in malignant tumors could be caused by mutations in the TET, IDH1 or IDH2 genes." (PMID 27050164, 2016). "Interestingly, mutations only in IDH1 and IDH2 have thus far been linked to cancer." (PMID 27196610, 2016). "In different cancer types, including HCC, a decreased level of 5hmC was shown to be caused by either reduced expression of the TET proteins or by inhibition of their activity by toxic metabolite α-hydroxyglutarate which is produced by gain-on-function mutant isocitrate dehydrogenases IDH1 or IDH2." (PMID 25918251, 2015). "Despite PROM1 having a poor prognostic value as a cancer stem cell marker, our finding that PROM1 expression is anti-correlated with IDH1 mutations supports a different biology for IDH mutant tumors and indicates that PROM1 expression may be most relevant in the non-IDH mutant setting." (PMID 25184684, 2014). "Mutation of these genes in cancer leads to a buildup of their substrates; fumarate and succinate in the case of FH and SDH mutations, or conversion of their regular substrate to a new “oncometabolite” in the case of mutant IDH1/IDH2 converting isocitrate to 2-hydroxyglutarate." (PMID 24350057, 2013). "By structural and functional analysis, IDH1 and IDH2 mutated cells gained the neomorphic enzymatic activity creating a condition with 2HG oncometabolite accumulation which promotes tumorigenesis through inhibiting a cancer-associated transcription factor such as hypoxia-induced factor (HIF)." (PMID 22397365, 2012). "To determine whether IDH1 and IDH2 mutants can dominantly inhibit the activity of endogenous IDH1 and IDH2 enzymes, we assayed NADP+-IDH activity of lysates of HOG cells overexpressing IDH1-WT, IDH2-WT, or cancer-derived IDH1 R132 and IDH2 R172 mutants in the presence of 40 μM isocitrate." (PMID 21326614, 2011). "Since then, numerous mutants in IDH1 and in the structurally and functionally similar mitochondrial enzyme IDH2 have been found in various cancers." (PMID 40943163, 2025).
cancer (continued). "The most clinically advanced example of targeting an oncometabolite is the inhibition of mutant IDH1 and IDH2 enzymes, which drive cancer through the aberrant production of 2-HG." (PMID 40931345, 2025). "In addition, by identifying cediranib as another agent that is synthetically lethal to IDH1-mutant cancers, and that can resensitize these resistant cancer cells to PARPi, this work may also provide the basis for new therapeutic strategies for patients with oncometabolite-producing malignancies." (PMID 41357766, 2025). "In cancer cells harboring mutant IDH1, SDH, or FH, excess oncometabolites (such as D-2-HG, succinate, or fumarate) accumulate, inhibiting PHD and FIH activity, thereby driving cancer progression and therapy resistance." (PMID 40487432, 2025). "To design a rational PARPi combination therapy, we screened a library of FDA-approved drugs and identified the mutant IDH1 inhibitor ivosidenib, which greatly potentiates PARPi efficacy in either BRCA1/2 wild-type (WT) or mutant cancer cells." (PMID 40299557, 2025). "IDH1 and IDH2 are also involved in glutamine metabolism, which is important in tumorigenesis as glutamine deprivation suppresses cancer growth." (PMID 39876890, 2024). "Reductive carboxylation from Gln-derived 2OG via IDH1 or IDH2 has been observed in brown adipose tissue and in cancer cells under deep hypoxia or with defective mitochondria." (PMID 39057706, 2024). "The knockdown of IDH1 leads to a decrease in NADPH and α-KG and an increase in ROS, leading to cancer cell apoptosis." (PMID 38674143, 2024). "EGCG in doses of 5–20 μM inhibited both IDH1 and GDH1/2, reduced proliferation and 2-HG production, making IDH-mutant cancer cells sensitive to irradiation." (PMID 38001865, 2023). "But at the same time, we found that the other two inhibition combinations, PLK1 combined with IDH1 and IDH1 combined with ACLY, were less effective in inhibiting the malignant phenotype of pan-cancer cell lines." (PMID 37958642, 2023). "Alterations in genes such as the FGFR, HER2, IDH1, and BRAF, result in cancer development, growth, and proliferation." (PMID 37046631, 2023). "We analyzed the expression levels of IDH1 in pathological stages and found that it was significantly overexpressed in stage III and IV in nine types of cancers." (PMID 37958642, 2023). "For example, c-MYC was determined to co-express with mutant IDH1/2 and increase the state of malignancy in MYC overexpressed cancers." (PMID 37110218, 2023). "Interestingly, the mutations in IDH1 and 2 do not impact cancer metabolism per se, as they rather cause the appearance of a neomorphic activity of IDH that perturbs the physiological oxidative decarboxylation of isocitrate to α-KG and promotes the reduction of α-KG to D-2-hydroxyglutarate (D-2HG)." (PMID 37561190, 2023). "Ivosidenib (AG-120) and enasidenib (AG-221) are now approved for treatment of IDH1- and IDH2-mutant cancers, respectively." (PMID 37705055, 2023).